BRCA1 (BRCA1 DNA repair associated)
Diseases named in the same sentence as BRCA1 in open-access papers (continued):
Sharing a sentence is not in itself a finding about the gene and the disease.
breast cancer (continued). "Given that Pit-1 down-regulates DNA-damage and repair genes (i.e. BRCA1) and sensitizes breast cancer cells to DNA-damage agents, in this study we used the antineoplastic drug, cisplatin, which is frequently applied to BRCA1-associated breast tumors." (PMID 25992773, 2015). "Several studies had been conducted for the relationship related to the BRCA1-associated breast cancers and therapeutic effects." (PMID 25695063, 2015). "The aim of this study was to differentiate between harmless deleterious mutations and polymorphisms in the BRCA1 gene of 154 females with breast cancer in the city of Bahía Blanca in Argentina, as well as cities in close proximity to Bahía Blanca." (PMID 25624909, 2015). "Mutation of BRCA1 raises the risk of breast cancer to 51% and 85% by the age 50 and 70 years, respectively; it also raises the risk of ovarian cancer to 23% and 63% by the age 50 and 70 years, respectively." (PMID 28316699, 2015). "Our findings demonstrate that high levels of Pit-1 and reduced BRCA1 levels increase breast cancer cell susceptibility to 3-Epi+cisplatin therapy." (PMID 25992773, 2015). "It is estimated that approximately 60 % of women who carry a mutated BRCA1/2 gene will develop breast cancer." (PMID 26236408, 2015). "This study analyzed TRα and TRβ immunopositivity in BRCA1 associated (n = 38) and sporadic breast cancer (n = 86)." (PMID 26029931, 2015). "One hundred eighty-three BRCA1/2 mutation carriers (64 %) were diagnosed with breast cancer between 1995 and 2000, and 104 (36 %) between 2001 and 2009." (PMID 25700605, 2015). "A clinical trial of a PARP inhibitor drug, Olaparib, based on the approach of synthetic lethality, has given successful results (minimal side effects with safely administrable doses) in breast cancers containing BRCA1/2 mutations." (PMID 25606064, 2015). "It is especially showing promise as single-agent treatment in patients with advanced ovarian and breast cancer harbouring deleterious BRCA1/2 mutations." (PMID 26610585, 2015). "RNA and protein analysis of a panel of breast cancer cell lines revealed that BRCA1 deficiency is associated with the downregulation of FOXA1 expression." (PMID 25531315, 2015). "Although somatic BRCA1 mutations are rare in sporadic breast cancer, BRCA1 expression is down-regulated in ~30% of sporadic cases by allele loss or epigenetic mechanisms." (PMID 26379698, 2015). "Here, we report two cases of patients with BRCA1 germline mutation treated for breast cancer who developed glioblastoma few years after breast cancer diagnosis." (PMID 25880076, 2015). "This approach is justified since post-menopausal breast cancer accounts for two-thirds of breast cancer cases amongst high risk women (with a 16-40% lifetime risk), 40% of cases amongst BRCA1 carriers and 50% of cases amongst BRCA2 carriers." (PMID 25648828, 2015). "TRβ positivity rate was significantly higher in BRCA1 associated as compared to sporadic breast cancers (p = 0.001)." (PMID 26029931, 2015). "Women carrying a germ-line mutation of BRCA1 are at much higher risk of developing an aggressive form of breast cancer when they are still young." (PMID 25762631, 2015). "High-risk women include those who have known genetic mutations (e.g., breast cancer susceptibility gene 1/2 [BRCA1/2]) or a strong family history of breast cancer." (PMID 25986460, 2015). "BRCA1/2 mutation is very uncommon in sporadic breast cancer, however, a quite high incidence (about 20%),of germ-line mutations in BRCA1 or 2 has been reported in patients with TNBC." (PMID 26387133, 2015). "The association between SNP genotypes and breast cancer risk was investigated by logistic regression adjusted for potential breast cancer risk factors and stratified by BRCA1/2 status and family history." (PMID 26517870, 2015). "From the HEBON subset of 329 women who were diagnosed with breast cancer between 1995 and 2009 in one of the participating hospitals, we included 287 BRCA1/2 mutation carriers." (PMID 25700605, 2015).
breast cancer (continued). "ANXA1 is overexpressed in familial breast cancer patients with BRCA1/2 mutations and correlated with poor prognosis features: triple negative and poorly differentiated tumors." (PMID 26137966, 2015). "In breast cancer cells, CaMKII triggers the export of breast cancer susceptibility gene 1 (BRCA1) from nucleus and decreases the BRCA1-dependent expression of p21CIP/KIP." (PMID 25961153, 2015). "French Canadian breast cancer and breast-ovarian cancer syndrome families of the province of Quebec harbour specific BRCA1 and BRCA2 mutations that recur in this demographically unique population due to founder effects attributed to common ancestors." (PMID 25884701, 2015). "Patients with deleterious mutations in either the BRCA1 or BRCA2 gene have a 50% to 80% lifetime risk of developing breast cancer and a 20% to 40% lifetime risk of developing ovarian cancer." (PMID 26295337, 2015). "Nonetheless, the degree to which family history of pancreatic cancer influences the likelihood of detecting a BRCA1/2 mutation in an individual with breast cancer is less clear." (PMID 26236408, 2015). "Simultaneously, a project led by George Church at Harvard University tried to correct genomic BRCA1(BREAST CANCER 1) mutations to decrease the risk of breast cancer in the next generation." (PMID 26473063, 2015). "In fact, this had been elegantly demonstrated through the preferential expression of HIF-1α in peri-necrotic/peri-fibrotic tumor cells in TNBC and BRCA1 mutated breast cancers." (PMID 26046764, 2015). "By contrast, in unselected women with early onset breast cancer BRCA1 mutations were found in 7.1% of patients." (PMID 26083025, 2015). "In this study we used a well-documented mouse breast cancer model that develops spontaneous tumors which share key features with BRCA1- associated breast cancer in humans." (PMID 25890200, 2015). "TN breast cancer patients with the BRCA1 gene mutations at the time of the diagnosis were younger than sporadic individuals (p = 0.0648)." (PMID 25705321, 2015). "The purpose of this study is to evaluate the association between ANXA1 expression, BRCA1/2 germline carriership, specific tumor subtypes and survival in breast cancer patients." (PMID 26137966, 2015). "This is consistent with the minor allele at rs10069690 conferring additional breast cancer risk in BRCA1 mutation carriers." (PMID 26053551, 2015). "Among the predictions, the product of the hyaluronan-mediated motility receptor (HMMR) gene, RHAMM, was found to be biochemically and functionally linked to the breast cancer gene, early onset 1 gene product (BRCA1)." (PMID 25830658, 2015). "In conclusion, this meta-analysis indicated that BRCA1 promoter methylation was associated with an increased risk of breast cancer." (PMID 26643130, 2015). "Nowadays, it is common knowledge that germ-line mutations of the BRCA1 gene are high risk factors for developing breast cancer." (PMID 25885115, 2015). "This work showed TRβ to be more frequently expressed in BRCA1 associated breast cancers as compared to sporadic breast cancer." (PMID 26029931, 2015). "This study indicated the role of TOX3 and FGFR2 as breast cancer susceptibility genes in BRCA1/2-wild-type breast cancer patients from Sardinian population." (PMID 25956309, 2015). "The basal-like subtype is frequent in women with BRCA1 germline mutations who are at markedly increased risk of breast cancer." (PMID 25825707, 2015). "The aim of this study was to utilize MR metabolomics to identify potential biomarkers of docetaxel resistance in a mouse model for BRCA1-mutated breast cancer." (PMID 25890200, 2015). "Women with germline mutations in BRCA1 have high risk of breast cancer (~80% by the age of 70), ovarian cancer (~30–40%) and other cancers." (PMID 25769025, 2015).
breast cancer (continued). "In the stratification analysis based on sample materials, the summary OR was 4.75 in tissues and 1.87 in peripheral bloods, indicating that the association of BRCA1 methylation with breast cancer risk in tissues was stronger than in peripheral bloods." (PMID 26643130, 2015). "BRCA1 gene mutation is closely associated with familial hereditary breast cancer, but the BRCA1 gene mutation is rarely found in sporadic breast cancer." (PMID 25789047, 2015). "Approximately, 7 % of all breast cancers (BC) and 11–15 % of ovarian cancers (OC) are associated with inherited predisposition, mainly related to germline mutations in high penetrance BRCA1/2 genes." (PMID 26669313, 2015). "Linkage studies in families with early onset breast cancer detected the presence of a breast cancer susceptibility gene, BRCA1." (PMID 25869442, 2015). "TNBC cases have similar histopathological and molecular features as those breast cancers that result from germline BRCA1 mutations." (PMID 26633365, 2015). "We have previously shown that BRCA1 carriers in our population have on average 25 % risk of developing breast cancer at 40 years of age." (PMID 26052370, 2015). "It is well-known that the majority of breast cancers that present in patients with positive BRCA1 mutations are TNBC." (PMID 25825688, 2015). "Discovering the significant contribution of BRCA1/2 mutations to breast cancer susceptibility allowed for the design of genetic tests that allows the medical practitioner to focus the care for those who need it most." (PMID 25923920, 2015). "We then evaluated the inhibition ability of HDAB to colony formation in MCF-7 (BCRA1 proficient breast cancer cell line) and MDA-MB-436 cells (BRCA1 deficient breast cancer cell line)." (PMID 26041102, 2015). "In this study, we explored mitochondrial haplogroups as potential modifiers of breast cancer risk in women carrying pathogenic BRCA1 or BRCA2 mutations." (PMID 25925750, 2015). "This is the basis for the concept that PARP inhibitors induce synthetic lethality in HR repair deficient tumors and provides a novel strategy for cancer therapy, at least in breast cancer patients who have mutations in BRCA1 or BRCA2." (PMID 25769025, 2015). "First, the status of the known breast cancer predisposition factors, mainly BRCA1 and BRCA2, was determined." (PMID 25923920, 2015). "While this PPV is relatively low due to the rarity of BRCA1 mutations in the population, its value is likely to improve in patients with a family history of breast cancer and/or early onset cancers." (PMID 26152113, 2015). "First and most importantly, there was large heterogeneity in the outcome of the association between BRCA1 promoter methylation and breast cancer risk." (PMID 26643130, 2015). "While current evidence suggests that hereditary breast cancer promoted by loss of Brca1 arises in luminal progenitor cells, the cell of origin for the majority of breast tumors, which are spontaneous in nature, remains undetermined." (PMID 26467658, 2015). "This conferred an approximate 95% reduction in breast cancer risk in BRCA1- and BRCA2-mutation carriers." (PMID 26557407, 2015). "High PIG3 and/or BRCA1 expression was also associated with better OS in human breast cancer patients." (PMID 25797244, 2015). "High resolution magic angle spinning (HRMAS) 1H MR spectroscopy was performed on tissue samples obtained from docetaxel-sensitive or -resistant BRCA1-mutated mammary tumors in mice." (PMID 25890200, 2015). "BRCA1/2-associated breast cancers account for about 25–30% of familial breast cancers, and for about 3% of all breast cancers." (PMID 25816289, 2015). "In fact, the prevalence of high penetrance breast cancer genes in our cohort was <1 % among those tested for BRCA1/BRCA2 mutations." (PMID 26673874, 2015).
breast cancer (continued). "Up to 30 % of ovarian cancer and TNBC patients show functional impairment of BRCA1/2 genes and women carrying BRCA1/2 germline mutations are at an increased risk of developing ovarian and breast cancer." (PMID 26510816, 2015). "Following on these observations, we further assessed the link between the AURKA-HMMR-TPX2-TUBG1 functional module and risk of breast cancer in BRCA1 or BRCA2 mutation carriers." (PMID 25830658, 2015). "Germline mutations in BRCA1/2 account for elevated sex steroid hormones and 2%–10% of breast cancer cases depending on ethnic origin." (PMID 26629528, 2015). "TNBC is characterized biologically by having a histopathological similarity with germline BRCA1-mutated breast cancer (BRCA-ness phenotype) with 90% of BRCA1-mutation tumors being considered as TNBC." (PMID 26267318, 2015). "In the subgroup analysis based on ethnicity, there were 15 studies in Caucasians, 4 in Asians and 2 in Australians for the association of BRCA1 methylation with breast cancer risk." (PMID 26643130, 2015). "Another potential limitation of our computer model is that we included prophylactic oophorectomy as a factor that predicts breast cancer reduction by 50% in BRCA1/2 mutation carriers." (PMID 26870808, 2015). "Here, we report the cases of two patients, with a germline BRCA1 mutation, who developed two primary breast cancers and a GBM." (PMID 25880076, 2015). "Germline mutations in BRCA1 or BRCA2 lead to a high lifetime probability of developing ovarian or breast cancer." (PMID 25859162, 2015). "Similar results were also observed by others for breast cancer patients carrying germline mutation in BRCA1." (PMID 25591549, 2015). "Significantly, this study identified TRβ to be up-regulated in BRCA1 associated breast cancer and revealed TRs to be associated with patients’ prognosis." (PMID 26029931, 2015). "The data presented in this manuscript suggests an interaction between the two pathways, as demonstrated by the enhanced protein levels of IGF-1R, p-IGF-1R, p-IRS-1, p-AKT and p-S6 in ovarian and breast cancer cells having loss-of-function mutations of BRCA1." (PMID 26510816, 2015). "It is estimated that 2 % of all breast cancers are directly attributable to inherited mutations in the breast cancer susceptibility gene BRCA1." (PMID 26152113, 2015). "As ILC risk is close to the overall breast cancer risk seen in carriers of BRCA1/BRCA2 mutations, it seems reasonable to offer the same type of surveillance as a routine procedure, and start screening at age 30 years with annual MRI and mammogram." (PMID 25848941, 2015). "In cultured cells, BRCA1-siRNA causes estrogen-independent ER activation and stimulates the agonist activity of Tam; and in Brca1-deficient mice, Tam promotes mammary cancer development." (PMID 26575173, 2015). "In our meta-analysis, 18 articles discussed the association of BRCA1 methylation with age at diagnosis in breast cancers." (PMID 26643130, 2015). "Mir-578, miR-573 and miR-122 were selected for validation on an independent set of 19 FFPE familial breast tumors subdivided into 8 BRCA1/2 related breast cancer cases and 11 BRCAX associated breast tumors." (PMID 25333258, 2015). "To ultimately define the role of UBE2T germline mutations in patients with breast/ovarian cancer, we performed whole exome sequencing using the Ilumina HiSeq platform on 450 BRCA1/2 WT high-risk breast cancer patients." (PMID 26085575, 2015). "Up to 5–10 % of all BC cases and 10–15 % of all ovarian cancer (OC) cases are due to germline mutations in one of the two breast cancer susceptibility genes, BRCA1 [MIM#113705] and BRCA2 [MIM#600185]." (PMID 26183948, 2015).
breast cancer (continued). "In conclusion, this study revealed multiple deregulated miRNAs in BRCA1/2-associated breast carcinomas, some shared with sporadic breast carcinomas, but several possibly specific to BRCA1/2 carcinogenesis." (PMID 26378051, 2015). "In this case-control study of women from high-risk breast cancer families, we confirmed that breast density was an independent risk factor for BC among BRCA1 and BRCA2 mutation carriers." (PMID 26163143, 2015). "Further explanations on the similarities and differences between miRNAs deregulated in sporadic and BRCA1/2-associated breast carcinomas will be made below." (PMID 26378051, 2015). "miR-99a was down-regulated in breast carcinomas compared to normal breast tissues in both BRCA1 and BRCA2 germ-line mutation carriers." (PMID 26378051, 2015). "Average age at diagnosis in the BRCA1-associated breast carcinomas was 46.1 years (range 21 - 81) in the first cohort, and 41.3 years (range 28 - 56) in the second cohort." (PMID 26378051, 2015). "The chromosomal location of 3 deregulated miRNAs (miR-100-5p, miR-125b-5p, and miR-150-5p) matches hotspot regions of genomic instability in BRCA1/2-associated breast carcinomas." (PMID 26378051, 2015). "Between 50% and 100% of these patients with BRCA1/2 mutations either had a personal history of breast carcinoma or at least a first degree relative with breast carcinoma or ovarian carcinoma." (PMID 26161390, 2015). "In fact, P-cadherin overexpression is mainly found in the triple-negative and basal-like subgroup of breast cancers and it is strongly correlated with the presence of BRCA1 mutations." (PMID 26438065, 2015). "Breast carcinomas showed extensive miRNA alteration compared to normal breast tissues in BRCA1 and BRCA2 mutation carriers." (PMID 26378051, 2015). "In previous work we identified a similar CNA devoid group of (BRCA1-mutated) basal-like breast carcinomas, which proved to be caused by the presence of large numbers of TILs in these samples." (PMID 26553136, 2015). "We also analyzed the associations of about 200,000 variants on the iCOGS genotyping array with subtype-specific breast cancer risk in carriers in an attempt to uncover previously unreported subtype-specific associations in women with BRCA1 and BRCA2 mutations." (PMID 25919761, 2014). "This study provides new insights into the causes and prognosis of DNMT1 inactivation in BRCA1-mutated breast cancer." (PMID 24502362, 2014). "Because the rs3734091-TT genotype was associated with an increased risk of non-BRCA1/2 breast cancer, we investigated the potential disease-inducing mechanism." (PMID 25360583, 2014). "Applying the BRCA1-mutation DNAme signature (out of the 1,829 BRCA1 CpGs, 1,722 were present on the 450 k Illumina methylation array), yielded a breast cancer risk AUC = 0.65 (0.51 to 0.78, P = 0.02)." (PMID 25067956, 2014). "Accumulating evidence indicates that an increased risk for breast cancer is associated with dietary factors and a few significant-risk genetic components (e.g., BRCA1)." (PMID 24675476, 2014). "Hereditary genetic factors are thought to account for approximately 5 to 10% of breast cancers due to germ-line variants in genes that increase the risk for breast cancer, such as BRCA1 and BRCA2." (PMID 25036186, 2014). "Recently, loss of BRCA1 function was shown to be associated with the expansion of breast cancer stem and progenitor cells, conferring a dependency on the expression of the polycomb repressor 2 complex protein EZH2." (PMID 25026298, 2014). "FANCJ is linked to cancer suppression and DNA double strand break repair through its direct interaction with the hereditary breast cancer associated gene product, BRCA1." (PMID 25374583, 2014). "TNBC is characterized biologically by having a histopathological similarity with germline BRCA1-mutated breast cancer, with 90% of BRCA1-mutation tumors being considered as TNBC." (PMID 25247558, 2014).